GDF15 (growth differentiation factor 15)
Diseases named in the same sentence as GDF15 in open-access papers (continued):
Sharing a sentence is not in itself a finding about the gene and the disease.
Obesity (continued). "Therefore, MT1‐MMP is thought to be a negative regulator of the GDF15‐GFRAL signalling pathway and may hence be a promising target for obesity treatment." (PMID 36992609, 2023). "Further, it is dimerized, cleaved, and secreted as mature GDF15, being considered an essential regulator of appetite through the glial-derived neurotrophic factor receptor alpha-like (GFRAL) and present at high levels in comorbidities such as obesity and diabetes." (PMID 37408184, 2023). "Growth differentiation factor 15 (GDF15), a divergent member of the transforming growth factor‐beta (TGF‐β) superfamily, has received appreciable attention in the last two decades for its multiple key role in several diseases, including obesity, cachexia, and cardiovascular disease." (PMID 34697897, 2022). "Furthermore, FGF21 and GDF15 have been reported to be elevated in a range of non-mitochondrial disorders, including cancers, obesity, renal diseases, diabetes, and liver diseases." (PMID 35498801, 2022). "However, the benefit of augmented FGF21 and GDF15 treatment in reducing risk for severe IAV and SARS-CoV-2 infection in obesity has not yet been explored." (PMID 34777390, 2021). "The fact that it signals via a specific hindbrain receptor, GFRAL, and that mice lacking GDF15 manifest diet-induced obesity suggest that GDF15 may play a physiological role in energy balance." (PMID 30639358, 2019). "Therefore, one would expect that the response of GDF‐15 to acute exercise—particularly high‐intensity interval exercise (HIIE), which imposes a higher metabolic challenge—would differ between individuals with prediabetes and individuals with obesity or type 2 diabetes." (PMID 41208056, 2025). "Thus, levels of GDF-15 may also rise in different conditions that are not related to CVDs, such as advanced age, obesity, diabetes, and kidney dysfunction, limiting its diagnostic value for CVDs." (PMID 35628490, 2022). "Besides the impact of GDF-15 on food intake contributing to the protection against obesity and T2D, anorectic-independent effects of GDF-15 on insulin sensitivity, lipolysis and fatty acid oxidation have been described, suggesting that GDF-15 effects extend beyond the regulation of food intake." (PMID 33302552, 2020). "Clinical evidence establishes a correlation between GDF-15 and subclinical atherosclerosis in specific clinical context; however, no research links GDF-15 to HF, obesity and subclinical atherosclerosis." (PMID 41597417, 2026). "Exercise suppresses appetite through modulators such as lactate, BDNF, sex hormones, growth differentiation factor 15 (GDF15), and asprosin, but is not closely related to GLP-1 in individuals with obesity." (PMID 40426650, 2025). "Furthermore, administration of a long-acting GDF15 molecule to non-human primates maintained the decrease in appetite and body weight for 4 weeks, suggesting this molecule might be used for chronic treatment of obesity." (PMID 37818094, 2023). "Growth differentiation factor 15 (GDF15) abundance in plasma of mice and humans induces negative energy balance but also becomes highly elevated in obesity and other metabolic diseases." (PMID 35510313, 2022). "Nonsteroidal anti-inflammatory drug-activated gene (NAG-1) or GDF15 is a divergent member of the transforming growth factor beta (TGF-β) superfamily and mice expressing hNAG-1/hGDF15 have been shown to be resistant to HFD-induced obesity and inflammation." (PMID 25239873, 2014).
diabetes (228 papers, 2013 to 2026). "Our results showed that circulating GDF15 levels were significantly higher in various indicators suggesting cachexia, such as advanced age, diabetes, and skeletal muscle loss which are important factors for sarcopenia." (PMID 41016991, 2026). "Increased GDF-15 levels have been observed in association with diabetes, smoking, surgical stress, intense physical activity, cancer, non-alcoholic fatty liver disease (NAFLD), as well as renal diseases." (PMID 41590509, 2026). "Random plasma glucose and prevalence of diabetes and cancer were positively associated with plasma GDF15 levels." (PMID 40527012, 2025). "Both eGFRdiff and GDF‐15 were independently associated with adverse outcomes in individuals with diabetes mellitus." (PMID 40700030, 2025). "Diabetes risk and frequency of metabolic syndrome as well as serum levels of prognostic markers NT-proBNP and GDF15 were similar in both groups." (PMID 40534909, 2025). "Considerable data indicate that metformin, a commonly prescribed medication for diabetes management, is associated with increased GDF-15 stimulation, subsequently improving glycemic control and inducing weight loss." (PMID 40722664, 2025). "In conclusion, as GDF15 and glycolipid are intimately linked, GDF15 can be used as a potential biomarker for the development of diabetes and MS." (PMID 41497484, 2025). "The positive association between diabetes and GDF15 was mediated 8.0% by TNFR1 and 1.3% by IL-6 independently." (PMID 41280118, 2025). "GDF-15 has been implicated in the development and progression of cardiovascular disease, diabetes, and cancer and is currently used as a predictive biomarker for the onset of proteinuria in diabetic nephropathy (DN)." (PMID 41019919, 2025). "Elevated GDF-15 levels (>1213.9 ng/mL) in our study were linked to older age, higher incidence of diabetes, systemic inflammation, renal impairment, and poorer exercise performance." (PMID 39334904, 2024). "The associations of GDF-15 extend across a spectrum of conditions, including diabetes mellitus, cancer, cachexia, chronic inflammatory diseases, cognitive impairment, heart failure, coronary artery disease, and atrial fibrillation." (PMID 38668313, 2024). "Circulating GDF-15 is more strongly associated with traditional CV risk factors, especially diabetes, LDL cholesterol, and physical activity than with specific indicators of atherosclerotic burden or cardiac dysfunction." (PMID 39780955, 2024). "Even though elevated GDF-15 levels have been suggested to have beneficial effects in diabetes, they have also been linked to increased mortality." (PMID 39000435, 2024). "Recent data corroborate these results, exhibiting that elevated serum GDF-15 levels are associated with death and vascular events within 3 months after IS in patients with diabetes." (PMID 39008451, 2024). "Altogether, our results demonstrated higher circulating GDF-15 levels are independently associated with severe COVID-19, including in patients with comorbidities including diabetes, cancer, COPD and CVD." (PMID 38686386, 2024). "Plasma levels of GDF-15 are more closely linked to traditional CV risk factors, such as diabetes, LDL cholesterol, and physical activity, than to direct indicators of atherosclerotic burden or cardiac dysfunction." (PMID 39780955, 2024). "High plasmatic GDF-15 levels are also found in association with impaired glucose tolerance, insulin resistance, diabetes, and diabetes-related complications, but its role in glucose homeostasis is unclear." (PMID 39000420, 2024). "GDF-15 has previously been demonstrated to be associated with future incident diabetes and to increase insulin sensitivity." (PMID 39780955, 2024). "Several investigations have linked elevated GDF-15 levels in the bloodstream to various age-related conditions, including cardiovascular diseases and diabetes, including in people living with HIV (PLWH)." (PMID 38686386, 2024).
diabetes (continued). "Growth differentiation factor 15 (GDF-15) has been suggested to have positive effects in diabetes, but is otherwise associated with adverse effects such as cardiovascular risk, declined kidney function, and neurodegeneration." (PMID 39000435, 2024). "We found that high GDF15 levels were associated with sarcopenia in patients with diabetes, and that GDF15 predicted incident frailty in a longitudinal study." (PMID 39375857, 2024). "Elevated GDF-15 is associated with incident diabetes in middle-aged adults (<60 years old) and metformin use." (PMID 37152099, 2023). "A variety of diseases have been reported to be associated with elevated GDF-15 blood levels, including chronic heart failure, coronary artery disease, chronic liver disease, chronic kidney disease, diabetes mellitus (DM), and tumor-induced anorexia." (PMID 37755357, 2023). "GDF15 is, together with its interaction partners, involved in the regulation of food intake and is found to be associated with diabetes and cardiovascular diseases in gene enrichment analysis." (PMID 37590326, 2023). "These advantages, combined with the positive correlation of serum GDF15 with FPG, HbA1c, and insulin resistance, make circulating GDF15 a promising diagnostic biomarker for diabetes or diabetes-related diseases." (PMID 36658625, 2023). "Elevated levels of GDF-15 were related to several cardiovascular risk factors, including the male gender, current smoking, body mass index, waist circumference, diabetes, fasting glucose, triglycerides, and low HDL cholesterol." (PMID 37888100, 2023). "Recent studies have consistently demonstrated the upregulation of GDF‐15 in aging and showed that higher GDF‐15 relates to higher risk of diabetes, cancer, cognitive impairment, cardiovascular diseases, and mortality." (PMID 36333824, 2022). "At baseline, high levels of GDF15 were associated with age, female sex, malnutrition, 6MWD, greater prevalence of comorbidities and diabetes mellitus." (PMID 36243733, 2022). "And increased concentrations of renin and growth differentiation factor 15 (GDF15) proteins and a lower adiponectin level were independently associated with coronary heart disease and diabetes mellitus." (PMID 34948066, 2021). "While the authors reported that the predictive power of GDF-15 was lost beyond 60 years of age, in PREDICTOR, a cohort with a mean age of 73, higher concentrations of GDF-15 were strongly associated with the presence diabetes mellitus." (PMID 34217226, 2021). "Age, creatinine, diabetes and atrial fibrillation were strongly, independently associated with GDF-15 in multivariate regression model (all p < 0.0001)." (PMID 34217226, 2021). "GDF15 levels were strongly correlated with age and positively correlated with cardiovascular risk factors (hypertension and diabetes) and inflammation (C-reactive protein: CRP > 3 mg/L)." (PMID 34445593, 2021). "Our findings confirm that metformin treatment is associated with GDF15 levels, but also clarifies that diabetes is associated with increased GDF15 levels even in the absence of metformin." (PMID 33279861, 2021). "The presence of diabetes mellitus was strongly associated with higher levels of GDF-15 and to a lesser extent of IGFBP7." (PMID 34217226, 2021). "Previous population-based studies have found that circulating GDF-15 levels are associated with cardiovascular risk factors such as age, current smoking, diabetes, and hypertension." (PMID 34177769, 2021). "Higher GDF-15 was associated with more patients with diabetes, angina pectoris, myocardial infarction, atrial fibrillation and COPD." (PMID 34217226, 2021). "Increasing levels of GDF-15 at presentation were associated with increased age, diabetes, hypertension, hyperlipidemia and a history of previous myocardial infarction and previous PCI/CABG." (PMID 32746821, 2020). "The relationship between GDF‐15 and age has been noted in a recent SomaScan study, as has been its association with diabetes, cardiovascular disease, and mortality." (PMID 33089916, 2020).
diabetes (continued). "GDF-15 levels are independently related to cardiovascular risk factors (diabetes, smoking, low HDL cholesterol) and biochemical risk markers (high-sensitivity C-reactive protein, NT-pro BNP) in elderly individuals and patients with coronary heart disease." (PMID 32466218, 2020). "There is growing evidence in both human and animal models that GDF15 plays an important role beyond cardiovascular disease and has been linked to weight homeostasis, fibrosis, diabetes, cardiovascular disease, renal disease, mobility disability and cancer." (PMID 33210602, 2020). "Previous investigations have also shown a positive association between GDF-15 concentrations and diabetes risk." (PMID 33239667, 2020). "Close associations between GDF-15 and increased risk of diabetes have been recently reported 6,9,12." (PMID 33239667, 2020). "Variables that were strongly associated with higher levels of GDF-15 in both cohorts were age, systolic blood pressure, diabetes mellitus and eGFR." (PMID 31263996, 2020). "In other cohorts of CKD patients, higher concentrations of GDF-15 were associated with female sex, older age, active smoking, and prevalent diabetes." (PMID 33419237, 2020). "Epidemiological studies consistently demonstrated that the expression of GDF15 is up‐regulated with aging and higher GDF15 relates to poor physical functions and higher risk of diabetes, cancer, cognitive impairment, cardiovascular diseases, and mortality." (PMID 32157804, 2020). "With respect to coronary risk factors, hypercholesterolemia and diabetes mellitus were significantly higher in the increased GDF-15 group (p: 0.024, p: 0.039, respectively)." (PMID 32466218, 2020). "As expected, circulating GDF15 levels have also been shown to help identify and predict cardiovascular disease risk in patients with diabetes." (PMID 32222153, 2020). "Significant association between GDF-15 and diabetes risk was found only in participants with fasting glucose <5.6 mmol/l (n = 3973)." (PMID 30350239, 2019). "The results of this cohort study showed that, in an urban population, circulating levels of GDF-15 were positively associated with the risk of incident diabetes, after controlling for traditional risk factors." (PMID 30350239, 2019). "When death from causes other than diabetes was accounted for as a competing event, the association between GDF-15 and the risk of diabetes was attenuated, but remained significant." (PMID 30350239, 2019). "By contrast, our results were derived from a large-scale cohort study, and showed that baseline GDF-15 was positively associated with the incidence of diabetes in the 19 year follow-up period." (PMID 30350239, 2019). "We observed significant interaction between GDF-15 and age in the association with incident diabetes (p for interaction <0.001)." (PMID 30350239, 2019). "In conclusion, the results of this study identified a positive association between baseline levels of circulating GDF-15 and diabetes risk in a 19 year follow-up period." (PMID 30350239, 2019). "GDF-15 levels are also associated with cardiovascular disease in individuals with established diabetes." (PMID 30350239, 2019). "Further studies are required to clarify the exact role of ageing in the association between GDF-15 and diabetes risk." (PMID 30350239, 2019). "The circulating GDF15 level was positively associated with age, smoking, hypertension, and diabetes mellitus as well as circulating levels of lipocalin 2 and various biomarkers of inflammation and oxidative stress." (PMID 28798540, 2017). "We observed a strong association between higher GDF15 concentrations and cardiometabolic risk factors, including hypertension, diabetes, smoking, and metabolic syndrome which precede the onset of overt cardiovascular diseases." (PMID 28798540, 2017).
diabetes (continued). "Ideally, these studies should specifically address diabetes mellitus as a potential confounder, because patients with diabetes mellitus also have increased GDF-15 and high risk of AKI after cardiac surgery." (PMID 27717384, 2016). "Growth differentiation factor 15 (GDF-15) is a member of the transforming growth factor ß family and has been associated with inflammation, cancer, aging, diabetes mellitus (DM) and atherosclerosis." (PMID 27056183, 2016). "There is very little information regarding pathophysiological role of GDF-15 in diabetes, CAD, hypertension, and diabetes associated with cardiovascular diseases." (PMID 26273671, 2015). "Increasing GDF-15 levels were associated with increasing age, diabetes, renal dysfunction, and inflammatory marker (CRP)." (PMID 26273671, 2015). "Our data showed that pre-operative GDF-15 levels in patients undergoing bypass surgery were positively associated with age, a history of diabetes, chronic renal failure, high NT-proBNP and plasma CRP levels." (PMID 25171167, 2014). "A medical history of diabetes mellitus was significantly associated with higher GDF-15 levels (p = 0.011)." (PMID 25171167, 2014). "There were significant independent associations between GDF-15 levels and current smoking, diabetes mellitus, and biomarkers indicating renal dysfunction (cystatin C), cardiac dysfunction (NT-proBNP, troponin T) and also inflammatory activity (CRP)." (PMID 24312445, 2013). "Recently, evidence indicates that circulating GDF15 concentration is closely associated with the development and prognosis of diabetes mellitus, and that overexpression of GDF15 can improve glucose tolerance." (PMID 23799024, 2013). "Macrophages from the kidneys of mice with diabetes are deficient in growth/differentiation factor-15 (GDF-15), which is required for oxidative metabolism in M2-like macrophages, resulting in a decrease in Klotho, an antiaging single-pass membrane protein that protects against AKI." (PMID 40362229, 2025). "Additionally, clinical studies also suggested that GDF15 mediates metformin-induced appetite suppression and weight loss among patients with diabetes." (PMID 40527012, 2025). "This indicates that the association between diabetes and GDF-15 levels varies by ethnicity." (PMID 40722664, 2025). "However, several prognostic factors such as B-type natriuretic peptide (BNP), tPA/PAI-1 complex, diabetes mellitus, cystatin C, and growth factor 15 (GDF-15) indicate an increased risk of unfavorable evolution in patients with HFpEF." (PMID 38255869, 2024). "As such, GDF-15 is also associated with several age-related diseases, including cardiovascular disease, cancer, metabolic syndrome, or diabetes, among others." (PMID 39644331, 2024). "That diabetes has been shown to have the strongest correlation to GDF-15 among other prognostic factors in a population with manifest PAD indicates that GDF-15 is linked to both diabetes and atherosclerosis and seems to be involved in the pathophysiology of both these entities." (PMID 39780955, 2024). "GDF-15 shares significant univariable and multivariable associations with both NT-proBNP and diabetes, so this may be explained by collinearity between the variables." (PMID 37567614, 2024). "Increased levels of GDF-15 in diabetes are often linked to vascular complications and mortality, and studies have shown that GDF-15 could be used to identify people at risk of glucose intolerance." (PMID 39000435, 2024). "Indeed, evidence from PIVUS study showed that high GDF15 was associated with higher prevalence of CV disease independent of traditional CV risk factors such as male gender, BMI, waist circumference, diabetes, fasting glucose, triglycerides, and low HDL." (PMID 39668628, 2024).